INS (insulin)
Diseases named in the same sentence as INS in open-access papers (continued):
Sharing a sentence is not in itself a finding about the gene and the disease.
Hypertension (continued). "Despite their higher-than-normal body fat mass, they are still insulin sensitive, with a favorable inflammatory and lipid profile and no signs of hypertension." (PMID 24550983, 2014). "This exaggerated enhancement of serum insulin levels in response to an oral glucose load, associated with similar renal sodium reabsorption in NI and HI subjects, separately, could not be enough to explain the high blood pressure development in our specific HI obese subgroup." (PMID 24966877, 2014). "For example, let us consider Hypertension as a disease and Insulin as a medication, although Insulin is not directly related with Hypertension; in most prescriptions both hypertension and insulin happen to be present." (PMID 24312659, 2013). "Reduction of aortic dilation to insulin, but not acetylcholine, prior to the onset of hypertension in the spontaneously hypertensive rats and in aged rats provides evidence that insulin resistance is an early event in the development of hypertension." (PMID 24194732, 2013). "The simultaneous effect of INT-747, a small molecule FXR agonist, on blood pressure and insulin sensitivity has not been studied before in Dahl Rats; an animal model that displays both systemic hypertension and IR." (PMID 23593273, 2013). "Compared with the NGT group, the body-mass index (BMI) and the prevalence of hypertension, previous PCI, oral hypoglycemic agents and insulin use were significantly higher, and the left ventricular ejection fraction was significantly lower in the DM group (P <0.05, respectively)." (PMID 23651930, 2013). "Because our analysis was retrospective, some additional useful data such as coexisting hypertension, serum cholesterol, or other serum adipokines such as leptin and adiponectin which regulate insulin sensitivity were not recorded in the dataset." (PMID 23786836, 2013). "Most of these studies included diabetics being treated with oral anti-diabetic agents and/or insulin therapy and did not exclude subjects with diabetic complications including cardiac disease, hypertension, and vascular disease." (PMID 24961266, 2012). "The use of MSG in genetically hypertensive rats led these animals to progressively increase body adiposity and hypertriglyceridemia; besides, developing and maintaining insulin resistance, low HDL-cholesterol, high blood pressure levels, and inflammation throughout the period studied." (PMID 22897936, 2012). "Both women and men with hypertension (irrespective of treatment or control) were older, had larger BMI, higher fasting glucose, insulin and triglycerides than those who were classified as normotensive." (PMID 21533232, 2011). "The reason why azelnidipine ameliorated glucose tolerance and insulin response in non-diabetic patients with essential hypertension should be discussed." (PMID 21906391, 2011). "This study is, to the best our knowledge, a first report that demonstrates the beneficial effects of azelnidipine on glucose tolerance and insulin sensitivity in non-diabetic patients with essential hypertension." (PMID 21906391, 2011). "Very recently, azelnidipine treatment have been shown to be useful in conditions like glucose tolerance, insulin sensitivity, inflammation, and number of circulating progenitor cells in non-diabetic patients with essential hypertension." (PMID 22054019, 2011). "The trend remained significant after additional adjustment for fasting plasma glucose/insulin, HOMA-beta/HOMA-IR, TC/TG, smoking, drinking and history of hypertension, and even in further stratification analysis by age, sex, BMI, smoking, drinking and history of hypertension." (PMID 20811623, 2010). "In a study of Japanese Americans, it was found that visceral fat was a significant correlate of hypertension and independent of fasting INS." (PMID 16076393, 2005).
Hypertension (continued). "Importantly, in this case–control study, the association between HOMA-IR and the left ventricular mass index was independent of age, duration of hypertension, BMI, waist circumference, and plasma glucose and insulin concentrations." (PMID 40283533, 2025). "Individuals in this low-income group were also more likely to have abdominal obesity, hypertension, chronic kidney disease, and a longer duration of T2DM (≥5 years), more likely to use statins, aspirin, oral anti-diabetic medications prescribed per year (at least three), and insulin treatment." (PMID 38972733, 2025). "Additionally, the DKD group showed significantly higher rates of hypertension and insulin use compared to the non-DKD group." (PMID 39850479, 2024). "However, guidelines for interpreting vitamin D levels must consider non-bone-related outcomes like hypertension, BMI, cardiovascular diseases (CVDs), and glucose and insulin metabolism measurements." (PMID 39015860, 2024). "Moreover, other researchers have observed similar plasma insulin levels in normotensive, nondiabetic individuals and those with hypertension, hinting at a possible inverse relationship between insulin and BP." (PMID 38711979, 2024). "The effect of joint IMIDs on the incidence of depression was more pronounced in men (p-interaction < 0.0001), patients without hypertension (p-interaction = 0.032), those not using insulin (p-interaction = 0.0013), and those who had a disease duration of T2DM of < 5 years (p-interaction = 0.0016)." (PMID 37138731, 2023). "It indicated the chronic TBF diet may ameliorate insulin-induced vasodilatation and insulin signaling pathways in the mesenteric arterioles of spontaneously hypertensive rats, illustrating that TBF could be used for the treatment of hypertension." (PMID 37476405, 2023). "The consumption of policosanol for 8 weeks by healthy female subjects with pre-hypertension resulted in lower blood pressure (BP) and CETP ability by elevating the HDL/apoA-I contents and enhancing the HDL functionalities, including cholesterol efflux and insulin secretion." (PMID 36982259, 2023). "The consumption of policosanol for 8 weeks by healthy female subjects with pre-hypertension resulted in a lower blood pressure and CETP ability by elevating the HDL/apoA-I contents and enhancing the HDL functionalities, including cholesterol efflux and insulin secretion." (PMID 36982259, 2023). "To assess whether and how ARBs restore impaired insulin signaling, we treated HepG2 cells for 16 h with 0.5 mM PA and three concentrations (5–20 μM) of nine FDA-approved ARBs that are commonly prescribed to treat hypertension in human patients." (PMID 37121975, 2023). "In addition, the OR was attenuated after further adjustment for hypertension, history of stroke, SBP, HbA1c, HDL-C, insulin or metformin usage and serum tHcy, in which the highest tertile of TyG index levels compared with the lowest had an OR of 1.933 (95% CI: 1.010 to 3.698; P for trend = 0.047)." (PMID 35992100, 2022). "The present investigation aimed to test whether the demands of exogenous insulin in GCs-treated women during pregnancy are different between those with gestational diabetes mellitus treated with αMD and women without hypertension." (PMID 35052298, 2022). "Most adult studies demonstrate that REM-predominant OSA is associated with excessive daytime sleepiness, non-adherence to continuous positive airway pressure, depression, hypertension, non-dipping of nocturnal blood pressure, increased insulin resistance, and impaired spatial navigational memory." (PMID 35573955, 2022). "However, the roles of exercise-induced changes in body composition, metabolic hormones (i.e., leptin and insulin) as well as their interactions with the RAS components and mediators of inflammation and oxidative stress in the sensitization of hypertension warrant further investigation." (PMID 35250473, 2022).
Hypertension (continued). "Finally, in insulin resistant individuals, altered targeting of IRAP may contribute to hypertension, as described." (PMID 36246906, 2022). "Moreover, we did not observe significant improvements in hypertension-related risk factors (including HOMA–IR) after WMT, although several studies have shown that FMT improves insulin sensitivity significantly." (PMID 34458158, 2021). "From these results, it was concluded that aging decreases insulin sensitivity even in essential hypertensive subjects and that insulin resistance does not affect the progression of cardiac hypertrophy or atherosclerosis in elderly subjects with essential hypertension." (PMID 35069451, 2021). "Our data shows that higher endogenous insulin secretion might play an important role in the progression of arterial stiffness in nondiabetic essential hypertensive patients." (PMID 34976408, 2021). "Subjects with IR differed significantly from those non-IR by age, total cholesterol, fasting glucose, fasting insulin, glycosylated hemoglobin, and prevalence of hypertension (p < 0.05), but not by sex, drinking, smoking, CRP, and other cardiovascular risk factors." (PMID 31249520, 2019). "Those with resolution were also more likely to be thinner with better metabolic profile (lower glucose, insulin, HOMA-IR, low-density lipoprotein [LDL], and triglyceride, and higher high-density lipoprotein cholesterol [HDL-C]) and lower prevalence of prediabetes and hypertension at baseline." (PMID 31308382, 2019). "However, the effectiveness of PCA administration on aging hypertension with regard to the vasorelaxant effects of insulin and IGF-1 and antioxidant activities has not been fully investigated." (PMID 30934575, 2019). "This included lower levels of insulin, glycated hemoglobin, blood glucose, inflammatory markers (IL-6 and CRP), and hemostatic factors (von Willebrand factor, factor VIII, tPA antigen, and D-dimer); a smaller waist circumference; and higher lung function and reduced odds of hypertension." (PMID 30124747, 2018). "In this study, we found an association between a high serum dioxin level (defined as a PCDD/Fs level ≥ 20 pg WHO98-TEQDF/g lipid) and CKD (defined as having an e-GFR ≤ 60 mL/min/1.73m2 or diagnosis of CKD by a physician), independent of gender, hypertension, insulin level, uric acid level, and age." (PMID 26963719, 2016). "Chocolate consumption has been associated with a short-term reduction in blood pressure and cholesterol, and improvement of insulin sensitivity; however, participants could not be aware of presenting hypertension or hypercholesterolemia." (PMID 25901348, 2015). "A positive correlation between LEP levels and heart rate has been reported in patients with hypertension, independent of other factors (BMI, age, insulin levels), which may suggest that increased LEP may increase BP." (PMID 26389928, 2015). "Also, their analyses were either not adjusted or did not adjust for hypertension, glycemic control, and insulin resistance." (PMID 25490096, 2014). "Despite having excessive body fat, these individuals display a favorable metabolic profile characterized by high levels of insulin sensitivity, no hypertension, normal lipid, inflammation, and hormonal profiles and, importantly in the context of the present study, a favorable immune profile." (PMID 22863368, 2012). "We hypothesized that azelnidipine administration could improve glucose tolerance and insulin levels in non-diabetic patients with essential hypertension." (PMID 21906391, 2011). "Moreover, 48.4% had hypertension, 29.2% fasting hypertriglyceridemia, 18.2% increased total cholesterol, 20.3% increased LDL cholesterol, 26.0% decreased HDL cholesterol, 81.4% increased HOMA-IR, 41.1% increased fasting insulin, and 35.6% impaired glucose metabolism." (PMID 37409224, 2023).
Hypertension (continued). "The number of participants who were taking medications to treat the following medical co-morbidities were: hypertension (7 control/6 patients), cholesterol lowering medications (6 control/6 patients) and oral anti-diabetogenic agents (0 control/2 patients), but none were taking insulin." (PMID 34518514, 2021). "However, comparison to our study may not be valid as not all patients were on regular insulin therapy and approximately one-third had vascular complications like hypertension, stroke, and impaired renal function." (PMID 32309448, 2020). "As dermcidin was capable of inhibiting insulin synthesis and as the lack of insulin synthesis was found to lead to increased dermcidin synthesis, a vicious circle would be implicated to worsen both T1BDM and hypertension due to the lack of systemic insulin synthesis." (PMID 24649391, 2014). "In addition, medications used for the treatment of angina may have other indications (e.g., hypertension), and are not unambiguously related to a single health condition like oral hypoglycemics or insulin." (PMID 22448755, 2012). "Pro467Leu, Val290Met, Phe388Leu, and Arg425Cysare all loss-of-function mutations (dominant negative) and have been associatedwith partial lipodystrophy, insulin resistance, diabetes, and hypertension, although it is not known whether theelevated blood pressure is due to impaired insulin sensitivity." (PMID 18288291, 2008). "The CKD group exhibited significantly higher values for age, BMI, WC, FBG, fasting insulin, HbA1c levels, TG, serum creatinine, BUN, UACR, UA, smoking history, and hypertension history compared to the non-CKD group (P< 0.05)." (PMID 40687590, 2025). "Additionally, the stronger association observed in non-hypertensive individuals may be explained by the absence of hypertension-related vascular endothelial dysfunction, which can impair skeletal muscle microcirculatory perfusion and limit insulin-mediated glucose uptake." (PMID 40948869, 2025). "Baseline biochemical parameters such as TG, non-HDL-C/HDL-C, TG/HDL-C, FPG, HbA1c, fasting insulin, and γ-GGT were also significantly higher in participants with stage 1 hypertension compared to those without (all p < 0.0001)." (PMID 40664455, 2025). "In 1988, Reaven described the insulin-stimulated glucose uptake resistance involved in the development of non-insulin-dependent diabetes mellitus (NIDDM), hypertension and coronary artery disease (CAD) as “syndrome x”." (PMID 40855011, 2025). "An association between a lower risk of MACEs and the use of GLP-1 RAs persisted regardless of hypertension, advanced CKD, or insulin/metformin use." (PMID 39003287, 2024). "Participants with hypertension had higher HOMA-IR, WC, BMI, WHR, BF%, SBP, and DBP, as well as higher TG, TC, fasting blood glucose (FBG), and fasting insulin levels, than those without hypertension (all P < 0.001)." (PMID 38102585, 2023). "In a study conducted in China, it has reported that a population of women with PCOS had higher levels of lipid, glucose, insulin, and HOMA-IR than women without hypertension." (PMID 35685525, 2022). "Physiologic parameters for blood pressure and glycaemic control (HbA1c, insulin, GLP-1) were not monitored in this healthy swine model and, therefore, clinical validation in patients with hypertension and T2DM is needed." (PMID 33635438, 2021). "Focusing on model fitness, no superiority was found between changes in fasting insulin, HOMA-IR, and IGR to predict incident hypertension." (PMID 31728151, 2019). "The most frequent components found were arterial hypertension or altered blood pressure (90%), increased WC (86%), and altered FBG or type 2 DM (without insulin use) (76%)." (PMID 28241426, 2017). "In the diabetic group, ischemia on MPI was not correlated with hypertension, smoking, family history of CAD, retinopathy, microalbuminuria, treatment modality for DM (oral antidiabetics, insulin, diet), and disease duration." (PMID 27277323, 2016).
Hypertension (continued). "The comparison of DM status, hypertension status, number of postmenopausal women, and serum levels of TC, TG, HDL-C, FBG, and insulin between the two groups showed no statistical difference." (PMID 26170530, 2015). "Schwimmer at al. showed that overweight children with NAFLD present higher fasting glucose, insulin, total cholesterol, LDL-cholesterol, triglycerides and high blood pressure than those without NAFLD." (PMID 24476029, 2014). "Similar to the differences seen at baseline, children with persistent high blood pressure had significantly higher values of GGT, LDL-cholesterol, insulin, and uric acid than children without persistent high blood pressure." (PMID 25419656, 2014). "Insulin also increases the release of IGF-1, which can lead to hypertension as a result of nonstriated-muscle hypertrophy." (PMID 22262974, 2012). "In addition, mental disorder accumulation had a stronger impact on the low-income group (Q1), with higher BMI (≥ 25 kg/m2), no-hypertension, no-CKD, no-CVD history, no-insulin use, less than three types of OHA use, and less than five years of DM group." (PMID 37208672, 2023). "We then included another twenty-two patients with nonfunctioning adenomas without abnormal glucose and lipid metabolism and hypertension and drew the curves of the OGTT (0 min, 30 min, 120 min) blood glucose and simultaneous insulin secretion of these three groups of patients." (PMID 34194493, 2021). "After 12 weeks of HFD consumption, plasma insulin, cholesterol, and triglyceride levels, as well as heart weight, body weight, and white adipose tissue (WAT) mass were increased in obese rats without hypertension (OB) and obese rats with hypertension (OH)." (PMID 29280941, 2017). "Notably, no statistical differences across groups were observed with respect to sex distribution, race distribution, smoking status, physical activity, hypertension prevalence, AST, LDL-C, insulin use and statin use showed no statistical differences across groups." (PMID 41341688, 2025). "Patients with hypertension (Class 3) were more likely to be male (OR [95 % CI]: 0.73 [0.56,0.95]), had higher TG (OR [95 % CI]: 1.09 [1.04,1.13]) and LDL (OR [95 % CI]: 1.39 [1.22,1.58]), and were more likely not to be treated with insulin (OR [95 % CI]: 1.78 [1.26,2.50])." (PMID 40084007, 2025). "Moreover, age, CAD history, hypertension, low cholesterol (including total, LDL, and HDL cholesterol) levels, increased UACR, use of insulin therapy and antihypertensive drugs, and no use of statins or metformin were significantly associated with high serum VCAM-1 levels." (PMID 39355615, 2024). "Similarly, the association between a lower risk of MACEs and the use of SGLT-2i was observed consistently among patients with hypertension and those using RAAS blockers, and in particular among patients with advanced CKD and those who were not receiving insulin or other OHAs or diuretics." (PMID 38170522, 2024). "The aim of the present study was to investigate in 152 pregnant women whether the demands of exogenous insulin in glucocorticoid-treated women during pregnancy are different between those with GDM and hypertension treated with αMD and those without hypertension." (PMID 35052298, 2022). "However, the proportion of patients prescribed insulin, oral hypoglycaemic agents, ACE inhibitors for those with albuminuria, aspirin for those with established CVD and treatment for hypertension and hyperlipidemia (statins) at year 2 was not significantly different to baseline." (PMID 17480239, 2007).